MDM2 (MDM2 proto-oncogene)
Diseases named in the same sentence as MDM2 in open-access papers (continued):
Sharing a sentence is not in itself a finding about the gene and the disease.
tumor (continued). "Currently, IHC of MDM2 and CDK4 may help screen for 12q13-15 amplification, which is seen in dedifferentiated tumours." (PMID 39011191, 2024). "Although the role of MDM2 in malignancy and tumor progression has been the focus of most previous studies, MDM2 has recently received increasing attention for its non-carcinogenic effects in various diseases and conditions, such as cardiovascular disease." (PMID 38640125, 2024). "Notably, in tumor-bearing mice, two highly conserved MHC I-binding motifs within MDM2, MDM2441 and MDM2100, elicit anti-tumor responses." (PMID 39263534, 2024). "Abemaciclib-treated patients suffering from luminal BC with HER4 expression or increased mdm2 gene copy numbers perform poorly compared to tumor patients without HER4 or mdm2 alterations." (PMID 39000582, 2024). "In addition to its oncogenic function, MDM2 can modulate the TIME, which consequently leads to immune tolerance and tumor evasion." (PMID 38281981, 2024). "As this tumor did not demonstrate overt lipomatous morphology, MDM2 reactivity was instrumental in arriving at a diagnosis of DDLPS of the rectum." (PMID 39165424, 2024). "In conclusion, MDM2 overexpression is an essential factor in the induction of HPD, which not only regulates the activation of T cells and cytokine secretion in the tumor immune microenvironment to reduce the efficacy of ICIs but also promotes tumor growth." (PMID 39263534, 2024).
tumor (continued). "Although MDM2 expression was noted with positive IHC in this case, the tumour was negative for amplification of the MDM2(12q15) locus by FISH." (PMID 36864468, 2023). "Notably, amplifications of CDK4 and MDM2 and gain of PDGFRA, together with chromosome 4p gain were identified as newly acquired CNAs in YMG25R, as compared to the initial tumor YMG25P." (PMID 38012788, 2023). "Tumor response to anticancer drugs may depend on the expression of apoptosis-related genes, such as SURVIVIN and MDM2." (PMID 38138884, 2023). "In addition, similar to YMG25R parent tumor, YMG25R xenograft cells highly expressed phospho-PDGFRA, -AKT, and -ERK as well as CDK4 and MDM2, and phospho-Rb, as compared to sham control." (PMID 38012788, 2023). "The clinical efficacy of MDM2 inhibition has been modest in STS and other tumor subtypes." (PMID 36464833, 2023). "On the other hand, MDM2 is an E3 ubiquitin ligase that mediates the interaction of Rb with the C8 subunit of the 20S proteasome, resulting in the ubiquitin-proteasome-mediated degradation of the RB1 tumor suppression protein." (PMID 37509256, 2023). "Our study further analyzed the signal pathways that may performed in the tumorigenesis and revealed the sensitivity of PCSK9 correlated with anti-tumor drugs in tumor treatment and their corresponding targets, such as PAK1, BCL2 and MDM2." (PMID 37860186, 2023). "MDM2 inhibitors, which target the E3 ligase mouse double minute 2 homologue (MDM2), and von Hippel–Lindau (VHL) tumor suppressor, which is the substrate recognition component of the E3 ligase complex VCB, are two examples of specific ligands that have been developed to bind to these ligases." (PMID 37241755, 2023). "We did not detect NTRK fusion or MDM2/CDK4 amplification in the residual tumor tissue, which was in line with the results of cfDNA-based assay at day 14 after resection." (PMID 36652666, 2023). "Immunohistochemically, the tumor cells were positive for Vimentin, S-100, CD34 and MDM2." (PMID 37670330, 2023). "Finally, the removed tumor tissue was subjected to western blot to verify the expressions of S100A6 and MDM2." (PMID 37217945, 2023).
tumor (continued). "Cell line and original tumor share the majority of CNV alterations, including losses in Chr 9/10 that included PTEN and MGMT and gains in Chr 20, which included amplification of PDGFRA, CDK4, and MDM2." (PMID 37958846, 2023). "The tumor specimen was sent for further analysis for next-generation sequencing (NGS; ACTOnco+, ACT Genomics), which mainly disclosed TPM3::NTRK fusion (Appendix Fig A1), and MDM2/CDK4 gene amplification." (PMID 36652666, 2023). "MDM2 amplification and MDM2 expression, respectively, did not correlate with overall or tumor-specific survival." (PMID 37821635, 2023). "A previous study has revealed that MDM2 could upregulate the transcription and translation of MYCN, an essential component to RB cell growth and tumor formation." (PMID 36741966, 2023). "The oncogenic signaling activation such as overexpression of MDM2 and EGFR could be triggering the acceleration of tumor growth." (PMID 35399666, 2022). "Defactinib induces dissociation of PI3K from FAK in esophageal squamous cell carcinoma, thus resulting in impaired AKT signaling and in the transcriptional downregulation of several oncogenes such as SOX2, MYC, EGFR, MET, MDM2 and TGFBR2, thus reducing tumor growth and metastatic ability." (PMID 35216114, 2022). "The expression of the MDM2 gene was negative correlated with age only in men (p-Value = 0.03) in tumour samples." (PMID 36551770, 2022).
tumor (continued). "Once MDM2 is overexpressed, RB expression drops and RB-mediated suppression of DNMT3A activity is diminished, which results in overactive DNMT3A catalyzing DNA methylation and silencing of tumor suppressor genes." (PMID 36296971, 2022). "In our study, all 18 tested WDLs were 12q13-15 amplified, including 17 MDM2-amplified cases and 1 FRS2-amplified/MDM2-nonamplified/CDK4-nonamplified tumor (case 4)." (PMID 36059611, 2022). "However, eight months after the initial diagnosis, this tumor was re-classified as DDLPS based on examination of the surgically excised tumor that showed focal well-differentiated LPS and the presence of MDM2 amplification by FISH analysis." (PMID 34986184, 2022). "As demonstrated in patient DDLPS1, the first two blood samples were positive for the presence of MDM2 amplification, before the resection of a large primary tumor that did not respond to the neoadjuvant therapy." (PMID 34986184, 2022). "A statistically significant negative correlation between patient age and MDM2 gene expression in tumour was found only in non-smokers (p-Value = 0.021)." (PMID 36551770, 2022). "Furthermore, the expression of MDM2 and RNF6 was increased in the tumor tissues in H. pylori and MNU group, and the effect was abrogated by GLA treatment." (PMID 35814430, 2022). "Among those are MDM2, DCAF15, DCAF16, RNF4, RNF114, FEM1B, KEAP1, AhR, cIAP1 and XIAP, which pose several distinct advantages including specificity for tissue, tumor, cell type or cell state, and synergistic tumoricidial effects through activation of pro-apoptotic cell cycle regulatory proteins." (PMID 36499765, 2022). "In particular, co-amplification of MDM2 and CDK4 is more prevalent in the low-grade parosteal OS (67%) compared to high-grade classical OS (12%), showing a correlation between amplification levels and tumor grading and progression in the former group." (PMID 35070121, 2022). "Since the bromodomain of BRD7 is critical for its tumor suppressor activity 10, 11, we then tested whether the bromodomain of BRD7 was required for the inhibition of MDM2 phosphorylation." (PMID 35371302, 2022). "The expression of MDM2 gene was negative correlated with age only in men (p-Value = 0.03) in tumour samples." (PMID 36551770, 2022). "The immunohistochemistry shows tumor cells positive for CDK4 and MDM2." (PMID 36093467, 2022). "In the present study, we evaluated whether the binding of MX25-1 to MYCN 3’UTR is able to block its interaction with MDM2 and inhibit both MYCN mRNA and MDM2 expression, resulting in tumor growth inhibition and cell death." (PMID 36505784, 2022).
tumor (continued). "The content of MDM2 oncogene as a proto-oncogene in normal tissues is very small, but the positive expression rate of MDM2 oncogene in NSCLC tissues increases with the increase of histological differentiation, and is significantly different from lymph node metastasis and tumor TNM stage." (PMID 36384712, 2022). "Further analysis revealed that CPPI blocked AR nuclear import and promoted AR degradation in the nuclear compartment through MDM2-dependent proteasome mechanism in CRPC cells (C4-2 and LNCaP95) and xenograft tumor models, leading to sharp retardation of tumor growth." (PMID 35372068, 2022). "Studies at home and abroad have found that cyclooxygenase-2 (COX-2), Ki67, vascular endothelial growth factor (VEGF), CD44V6, epidermal growth factor receptor (EGFR), double microsome 2 (MDM2) and transforming growth factor TGF-β1 have certain clinical significance in tumor growth." (PMID 36384712, 2022). "A first-in-class MDM2 degrader using proteolysis targeting chimera (PROTAC) concept, MD-224, was shown to be highly potent in inducing MDM2 degradation and achieving durable tumor regression in vivo." (PMID 35155432, 2022). "Mouse double minute 2 homolog (MDM2) fluorescence in situ hybridization (FISH) was negative for malignant lipomatous tumor." (PMID 34348760, 2021). "Indeed, the MDM2 inhibitor, CGM097, in combination with a CDK4/6 inhibitor palbociclib and fulvestrant has shown promising therapeutic benefits in reversing the tumor resistance to CDK4/6 inhibitors and to endocrine therapy." (PMID 34123801, 2021). "MDM2 testing of the tumor was positive in 88 patients (46.3%), and 102 patients (53.7%) did not have MDM2 testing performed." (PMID 34671190, 2021). "Furthermore, nutlin-3a was ineffective in tumours overexpressing MDMX, and this resistance was reversed following deletion of the MDMX RING domain that is important for the interaction with MDM2." (PMID 34911439, 2021).